PPL (periplakin)
Description:
Component of the cornified envelope of keratinocytes. May link the cornified envelope to desmosomes and intermediate filaments. May act as a localization signal in PKB/AKT-mediated signaling.
Tractability: Antibody: its Gene Ontology location is reachable by antibodies, with high confidence; UniProt places it where antibodies can reach, with medium confidence. PROTAC: ubiquitination databases record sites on it; its protein half-life has been measured.
Gene: Protein-coding gene on chromosome 16 (4,882,507 to 4,960,741, reverse strand). Ensembl gene ENSG00000118898.
Subcellular location: Cell junction, desmosome; Cytoplasm, cytoskeleton; Cell membrane; Lateral cell membrane; Cytoplasm
Subcellular location (Human Protein Atlas): Basal body; Cytosol; Plasma membrane; Nucleoplasm
Pathways (Reactome):
Developmental Biology: Formation of the cornified envelope
Immune System: Butyrophilin (BTN) family interactions
Gene Ontology:
Molecular function: cadherin binding; protein binding; structural constituent of cytoskeleton; structural molecule activity
Biological process: response to mechanical stimulus; intermediate filament cytoskeleton organization; wound healing
Cellular component: extracellular exosome; cornified envelope; cytoplasm; cytoskeleton; cytosol; intermediate filament; lateral plasma membrane; membrane; plasma membrane; desmosome
Genetic constraint (gnomAD): Loss-of-function variants: 192 observed, 186.5 expected, observed/expected ratio (o/e) 1.03, 90% interval 0.91 to 1.16. The synonymous counts are far from expectation, so gnomAD's model fits this gene poorly and the ratio says little. Missense variants: 2,849 observed, 2,303.8 expected, observed/expected ratio (o/e) 1.24, 90% interval 1.2 to 1.27. Synonymous variants: 1,207 observed, 981.52 expected, observed/expected ratio (o/e) 1.23, 90% interval 1.17 to 1.29.
Homologues: Orthologues: chimpanzee PPL (99% identical), macaque PPL (97% identical), mouse Ppl (88% identical), rat Ppl (88% identical), guinea pig PPL (88% identical), pig PPL (88% identical), dog PPL (87% identical), rabbit PPL (84% identical), tropical clawed frog ppl (64% identical), zebrafish ppl (54% identical). Paralogues in human: EVPL (30% identical), EVPLL (5% identical).
Diseases named in the same sentence as PPL in open-access papers:
PPL is named in the same sentence as 61 diseases in open-access papers, as found by Europe PMC text mining. Sharing a sentence is not in itself a finding about the gene and the disease. The quoted sentences say what the papers report.
esophageal cancer (8 papers, 2007 to 2025). A primary or metastatic malignant neoplasm involving the esophagus. "Loss of PPL may be one of the early events in the progression of oesophageal cancer." (PMID 35612641, 2022). "Periplakin is a potential marker for detecting early esophageal cancer and evaluating tumor progression." (PMID 41169522, 2025). "It was reported that the expression of PPL was significantly decreased in esophageal cancer tissues and that the proteins were barely detectable in advanced cancer samples." (PMID 36298586, 2022). "Although previous research observed that the expressions of PPL were significantly lower in a variety of tumors than that in the adjacent tissues, like advanced-stage of urothelial bladder cancer and human esophageal cancers." (PMID 35612641, 2022). "Consistent with oesophageal cancer, in urothelial carcinoma of the urinary bladder, the expression of PPL was reduced with increasing pathological stages." (PMID 34001250, 2021). "In particular, the expression level of two proteins, periplakin and clusterin, were nearly zero in esophageal cancers when compared to healthy tissue." (PMID 27053248, 2016). "The levels of periplakin were found to have shifted from the cell–cell boundary of normal esophageal epithelial cells to the cytoplasm of epithelial cells in early esophageal cancer, then to have disappeared completely in advanced esophageal cancer." (PMID 27053248, 2016). "Since PPL expression is decreased in esophageal carcinoma tissues, we tried to determine the effects of PPL downregulation on cancer cell activities." (PMID 21951621, 2011). "Among them, periplakin was significantly down-regulated in esophageal cancer, which was confirmed by immunoblotting and immunohistochemistry." (PMID 17407558, 2007). "We may be able to use periplakin and clusterin to assess changes in patients with esophageal cancers." (PMID 27053248, 2016). "Thus PPL could be a useful marker for detection of early esophageal cancer and evaluation of tumor progression, but largely remains unknown in this field." (PMID 21951621, 2011). "According to xiantao database, PPL, PI3, LCE3E, and TGM1 were more expressed in esophageal cancer than normal tissues (p < .05)." (PMID 38241178, 2024). "The positively correlated genes (SLUT2B1, PPL, KLK6, CRYBG2, SCEL, ADGRF4 and KLK8) were more frequently expressed in esophageal cancer than normal tissue (p < .05)." (PMID 38241178, 2024). "In cancer, reduced expression of PPL and EVPL have been observed in oesophageal cancers, and the cellular localisation of PPL was noted to change with disease progression." (PMID 34001250, 2021). "We previously reported that a cell adhesion molecule, periplakin (PPL), is significantly downregulated in human esophageal cancers." (PMID 21951621, 2011).
ovarian carcinoma (6 papers, 2011 to 2025). A malignant neoplasm originating from the surface ovarian epithelium. "In this review article, we explore the roles of plakins, particularly plectin, periplakin and envoplakin in disease-states and cancers with emphasis on ovarian cancer." (PMID 34001250, 2021). "Since PI3K/Akt/mTOR pathway inhibition is reported to decrease invasion and migration of ovarian carcinoma cell lines, thus PPL siRNA potentially decreased cellular attachment, migration or movement at least partly via the PI3K/Akt axis." (PMID 21951621, 2011). "In addition, the previous study also lacked a detailed demonstration of PPL expression in different stages, grades, and Types of ovarian cancer to portray the epithelial-cell confinement of PPL expression." (PMID 39682273, 2024). "We attempted to understand the correlative relationship between the expression of plakins (PPL, PLEC, and EVPL) and the process of EMT by using immunohistochemistry and mRNA analysis on ovarian tumours, ovarian cancer cell lines, and in silico analyses." (PMID 39682273, 2024). "We have recently shown the expression of PLEC, PPL, and EVPL in benign and malignant ovarian tumours." (PMID 39682273, 2024). "Here, authors identified eight genes, including PPL and PKP3, whose increase expression in human melanoma metastases and ovarian cancers was associated with a lack of Th1 immune signatures and further strongly correlated with shorter overall survival." (PMID 34060699, 2021).
pharyngeal cancer (3 papers, 2011 to 2019). "In pharyngeal cancer cells, PPL knockdown is related to reduced cellular movement and attachment activity." (PMID 25583674, 2015). "Further studies are required to investigate the role of PPL as a candidate biomarker for diagnosis and treatment of pharyngeal cancers." (PMID 21951621, 2011). "Our results indicate that PPL downregulation is accompanied by PI3K/Akt axis interference which indicates EMT in pharyngeal cancers." (PMID 21951621, 2011). "Furthermore, distinct from the previous report using pharyngeal cancer cells using siRNA of PPL 8, we found that PPL induction inhibited migration of ESCC, which is a feature of epithelial–mesenchymal transition, the hallmark of metastatic cancer." (PMID 25583674, 2015). "We found that PPL knockdown was related to a reduction in cellular movement and attachment activity, and was accompanied by PI3K/Akt axis suppression in pharyngeal cancer cells; it was potentially related to EMT promotion." (PMID 21951621, 2011). "PPL knockdown is therefore related to reduced cellular movement and attachment activity rather than malignant progression, that is, PPL potentially participates in EMT in pharyngeal cancer cells." (PMID 21951621, 2011). "PPL knockdown is related to reduced cellular movement and attachment activity in association with PI3K/Akt axis suppression, rather than malignant progression in pharyngeal cancer cells." (PMID 21951621, 2011).
urothelial bladder cancer (3 papers, 2021 to 2024). "Among other plakin proteins, periplakin expression has been reported to decrease in urothelial carcinoma of the bladder." (PMID 39052015, 2024). "For example, lower expression of PPL is related to cancer-specific survival and pathological stage in urothelial carcinoma of the urinary bladder." (PMID 34131588, 2021).
autosomal dominant polycystic kidney disease (2 papers, 2020 to 2023). Autosomal dominant form of polycystic kidney disease. "This suggests that envoplakin, periplakin, and villin-1 may be used as biomarkers to differentiate between autosomal dominant polycystic kidney disease (ADPKD) patients with or without CKD." (PMID 37510273, 2023).
bladder cancer (2 papers, 2018 to 2022). "Interestingly, a downregulation of periplakin was observed in urinary bladder cancer, esophageal squamous cancer, and colon carcinoma, pointing to periplakin’s role as a cancer suppressor." (PMID 29587367, 2018).
colon carcinoma (2 papers, 2018 to 2021). "On the contrary, in a colon cancer cell line model (HT29), increased proliferation, migration, invasion and EMT initiating ability was noted in response to PPL knockdown." (PMID 34001250, 2021). "However, the process was reversed in terms of decreased proliferation, migration and EMT ability when PPL was overexpressed in the same cell line, strongly suggesting an inverse relationship of PPL expression and induction of EMT in colon cancer cells." (PMID 34001250, 2021).
colorectal cancer (2 papers, 2024 to 2025). A primary or metastatic malignant neoplasm that affects the colon or rectum. "This is consistent with work in colorectal cancer demonstrating that loss of PPL increases EMT potential, and PPL overexpression limits both tumour cell proliferation and EMT marker expression." (PMID 39682273, 2024).
diabetes (2 papers, 2020 to 2023). "These bioactive components appear to be capable of inhibiting three essential metabolic enzymes associated with diabetes: porcine pancreatic α-amylase (PPA), dipeptidyl peptidase-IV (DPP-IV), and pancreatic lipase (PPL)." (PMID 38274210, 2023).
esophageal squamous cell carcinoma (2 papers, 2015 to 2018). Esophageal squamous cell carcinoma (ESCC) is a type of esophageal carcinoma (EC) that can affect any part of the esophagus, but is usually located in the upper or middle third. "Although PPL downregulation is clearly associated with cancer progression and malignancy, knowledge of its contribution to the malignant property of esophageal squamous cell carcinoma (ESCC) is limited, and the molecular mechanism underlying the regulation of PPL expression is largely unknown." (PMID 25583674, 2015). "Periplakin (PPL), a member of the plakin family of proteins that localizes to desmosomes and intermediate filaments, is downregulated in human esophageal squamous cell carcinoma (ESCC)." (PMID 25583674, 2015).
gastric cancer (2 papers, 2022 to 2025). A primary or metastatic malignant neoplasm involving the stomach. "In advanced gastric cancer (pathologic stages III and IV) patients, the post-operative expression levels of PPL/GAPDH, miR140-5p/miR197, and miR301a/miR197 were significantly increased compared with the pre-operative levels." (PMID 40429589, 2025). "This study showed that three mRNAs (SPINK7, PPL, and SEMA4B) and two miRNAs (miR140-5p and miR301a) were significantly downregulated in gastric cancer patients." (PMID 40429589, 2025). "A previous study on salivary exRNA biomarkers showed that three mRNAs (SPINK7, PPL, and SEMA4B mRNAs) and two miRNAs (miR140-5p and miR301a) were significantly down-regulated in gastric cancer patients compared with healthy individuals in a Korean population." (PMID 40429589, 2025). "For example, in a study, 5 exRNAs, including 3 mRNAs (SPINK7, PPL, and SEMA4B) and 2 microRNAs (MIR140-5p and MIR301a), showed downregulation in gastric cancer (GC)." (PMID 35948986, 2022).
glioma (2 papers, 2021 to 2022). A benign or malignant brain and spinal cord tumor that arises from glial cells (astrocytes, oligodendrocytes, ependymal cells). "Overexpression of PCDH18, PPL, DEPP1, VASN, KCNE4, MYBPH, and C5AR2 in glioma and low expression of MARCH4 were associated with poor survival." (PMID 39281062, 2022). "Through TCGA database, we identified that the eight key genes (PCDH18, PPL, DEPP1, VASN, KCNE4, MYBPH, C5AR2, and MARCH4) were associated with the survival of patients with glioma." (PMID 39281062, 2022). "Overexpression of PCDH18, PPL, DEPP1, VASN, KCNE4, MYBPH, and C5AR2 genes or low expression of MARCH4 gene in glioma patients was associated with poor survival." (PMID 39281062, 2022).
Hepatic fibrosis (2 papers, 2013 to 2023). The presence of excessive fibrous connective tissue in the liver. "Second, the expression of PPL was examined in models with chronic damages from hepatic fibrosis or steatosis." (PMID 23849208, 2013). "Furthermore, similar hepatoprotective effects were replicated in dimethyl nitrosamine (DMN)-induced liver fibrosis, and the biological function of this phenotype identified that PPL restraining the transformation of hepatic stellate cells to fibroblasts." (PMID 37033635, 2023).
paraneoplastic pemphigus (2 papers, 2012 to 2018). Pemphigus is a group of chronic autoimmune skin diseases characterized by blisters formation on the outer layer of the skin and the mucous membranes. "A cumulative autoimmune response to periplakin, envoplakin, BPAG1, and desmoplakin has been described in persons affected by paraneoplastic pemphigus that results in a dismal prognosis with a 75–90% mortality rate and a mean survival < 1 year." (PMID 29373494, 2018).
pemphigus (2 papers, 2012 to 2024). Pemphigus is a group of rare autoimmune diseases that cause blistering of the skin and mucous membranes (mouth, nose, throat, eyes, and genitals).This conditioncan occur at any age, but often strikes people in middle or older age. "Furthermore, the rat bladder is rich in plakins such as envoplakin and periplakin, making it highly specific for differentiating PNP from other forms of pemphigus." (PMID 39584995, 2024).
skin cancer (2 papers, 2018 to 2024). "In contrast, another mouse model deficient in envoplakin, periplakin, and involucrin (Epi−/− mice), three components of the epidermal barrier on which the cornified envelope assembles, have a defective epidermal barrier that is protective against skin cancer." (PMID 39625985, 2024).
B-cell lymphomas (1 paper, 2016). "In order to investigate whether PpL was able to induce alterations in the level of expression of the BCR receptor of murine B-cell lymphomas, A20, LBK, and the κ- LBO lymphoma cells were cultured in the presence of 100 μg/ml of PpL during 60 min." (PMID 27603942, 2016).
cervical dysplasia (1 paper, 2021). "Five out of ten consistently upregulated genes (CEBPD, KRT16, SLPI, RPS29, and PPL) were also increased in cervical dysplasia." (PMID 34944802, 2021). "SLPI and PPL exhibited a drastic shift in their expression patterns from cervical dysplasia to cancer, expressing at low levels." (PMID 34944802, 2021).
cholestasis (1 paper, 2013). Impairment of the bile flow caused by obstruction within the liver, or outside the liver in the bile duct system. "Expression of PPL during cholestasis induced by the administration of CA through the diet (0.1%–1% for 7 days) was also evaluated in the liver of wild-type mice." (PMID 23849208, 2013). "The clarified pattern of expression of PPL in these mice suggested that PPL plays an important role in the temporal accommodation to cholestasis." (PMID 23849208, 2013). "The expression of PPL during dietary CA-induced cholestasis was determined by immunohistochemical examination in wild-type mice." (PMID 23849208, 2013). "Notably, the accumulation of PPL following BDL was observed as early as 2 days post-ligation, suggesting a role for PPL in early response to cholestasis." (PMID 23849208, 2013). "Because we observed a marked fluctuation of PPL expression in mouse liver in association with the bile acid receptor farnesoid X receptor (FXR) and cholestasis, we sought to characterize the role of PPL in the liver and determine its contributions to the etiology and pathogenesis of cholestasis." (PMID 23849208, 2013). "Examination of hepatic gene expression profiles of Fxr null (Fxr−/−) and wild-type mice, and comparison with the expression of selected genes in a cholestatic mouse model (dietary cholic acid [CA]-administration), revealed that periplakin (PPL) is a unique protein central to FXR and cholestasis." (PMID 23849208, 2013). "Lastly, expression of PPL in cholestatic mouse models was investigated using ANIT and BDL; these approaches induce 2 distinct types of cholestasis, cholangiocellular injury-derived (intrahepatic) and obstructive (extrahepatic) cholestasis, respectively." (PMID 23849208, 2013). "Notably, the mRNA and protein levels of PPL were not completely paralleled, suggesting the importance of post-transcriptional regulations of PPL expression in response to cholestasis." (PMID 23849208, 2013).
Hepatic steatosis (1 paper, 2023). Steatosis is a term used to denote lipid accumulation within hepatocytes. "However, the specific role and regulatory mechanisms of PPL in ameliorating HFD-induced hepatic steatosis and injury remain elusive." (PMID 37033635, 2023).
Hyperkeratosis (1 paper, 2016). Hyperkeratosis is a histopathological term defining a thickened stratum corneum and may be present in many different skin conditions, with many possible overlaps. "Moreover, mice deficient in INVOLUCRIN, ENVOPLAKIN, and PERIPLAKIN show barrier defects, decreased desquamation, and hyperkeratosis that is concomitant with decreased KLK activity." (PMID 27551807, 2016).
invasive carcinoma (1 paper, 2019). A carcinoma that is not confined to the epithelium, and has spread to the surrounding stroma. "Periplakin was expressed very heterogeneously in both dysplasia and invasive tumor areas, often with no clear differences between dysplasia and invasive tumor, with a tendency toward having higher expression in invasive carcinoma." (PMID 31454186, 2019).
keloid (1 paper, 2022). An irregularly shaped, elevated mark on the skin caused by deposits of excessive amounts of collagen during wound healing. "Most keratins and cell junction related proteins such as KRT10, EVPL, PPL, and DSP were downregulated in keloids." (PMID 35435317, 2022). "Moreover, several proteins that play a role in cell junctions were also downregulated in keloids, including EVPL, PPL, DSP, PKP1, PKP3, DSC1, DSG1, and FLG." (PMID 35435317, 2022).
lung carcinoma (1 paper, 2022). "The higher level of PPL protein was shown in a part of cancers than that in normal tissues, such as thyroid cancer, lung cancer, and OV." (PMID 35612641, 2022).